YTHDF2 (YTH N6-methyladenosine RNA binding protein F2)
Diseases named in the same sentence as YTHDF2 in open-access papers (continued):
Sharing a sentence is not in itself a finding about the gene and the disease.
hepatocellular carcinoma (continued). "In hepatocellular carcinoma (HCC), METTL3 has been reported to promote tumor cell proliferation through the YTHDF2-dependent silencing of SOCS2, resulting in the overactivation of the JAK/STAT pathway." (PMID 40136363, 2025). "In an HBV-related hepatocellular carcinoma (HCC) model, YTHDF2 stabilizes MCM2 and MCM5 transcripts in an m6A-dependent manner." (PMID 40271153, 2025). "In hepatocellular carcinoma (HCC), YTHDF2 promotes tumor progression by orchestrating immune evasion and angiogenesis." (PMID 41403953, 2025). "A recent study on hepatocellular carcinoma (HCC) found that ferroptosis is regulated by the PPARGC1A/BAMBI/ACSL5 axis, with METTL3 and WTAP inhibiting PPARGC1A in an m6A- and YTHDF2-dependent manner." (PMID 40271153, 2025). "YTHDF2 stabilizes the transcription of maintenance protein 2 (MCM2) and maintenance protein 5 (MCM5) in microchromosomes, promoting hepatocellular carcinoma progression in hepatitis B virus-infected individuals." (PMID 38711079, 2024). "OGT-mediated O-GlcNAcylation of YTHDF2 enhanced its protein stability and oncogenic activity by inhibiting YTHDF2 ubiquitination and then promoted HBV-related hepatocellular carcinoma progression in an N6-methyladenosine-dependent manner." (PMID 38575607, 2024). "Studies demonstrated that m6A binding protein YTHDF2 destabilized EGFR via binding to m6A site, and inhibited hepatocellular carcinoma cells." (PMID 36816363, 2023). "Otherwise, in hepatocellular carcinoma (HCC), YTHDF2 acts as a tumor suppressor and promotes the degradation of epidermal growth factor receptor (EGFR) mRNA, and negatively modulates its stability." (PMID 35327559, 2022). "Overexpression of m6A reader YTHDF2 inhibits the activation of MEK and ERK which are downstream of Ras and impairs hepatocellular carcinoma progression." (PMID 34484567, 2021). "YTHDF2 can regulate the level of m6A in hepatocellular carcinoma (HCC), and miR-145 participates in the regulation of m6A mRNA by targeting YTHDF2 mRNA." (PMID 34794452, 2021). "Overexpression of METTL3 significantly promoted tumorigenesis and metastasis of hepatocellular carcinoma, mostly through regulation of SOCS2 expression by an m6qa- and YTHDF2-dependent mechanisms." (PMID 33692753, 2021). "In addition, YTHDF2 plays a critical role in vascular reconstruction in hepatocellular carcinoma (HCC)." (PMID 34221238, 2021). "Studies have shown that YTHDF2 induced the targeted degradation of the tumor suppressor SOCS2, thereby promoting the tumor progression of hepatocellular carcinoma, and this regulation depended on the m6A modification induced by METL3." (PMID 33505426, 2020). "It was reported that miR-145 reduced YTHDF2 expression by targeting its 3′ UTR, leading to increased m6A mRNA levels in hepatocellular carcinoma (HCC) cells." (PMID 31757221, 2019). "In human hepatocellular carcinoma (HCC), highly expressed METTL3 restrains expression of SOCS2 via YTHDF2-mediated degradation." (PMID 31801551, 2019). "In addition, a decrease in YTHDF2 might initiate several inflammation reactions in hepatocellular carcinoma (HCC)." (PMID 40218916, 2025). "For example, in hepatocellular carcinoma (HCC), the recognition protein YTHDF2 directly recognises and binds to the m6A modification site of epidermal growth factor receptor (EGFR), destabilising and degrading it, thereby inhibiting cell proliferation and growth." (PMID 38572667, 2024). "Moreover, sWGA pull-down assays in hepatoma cells and HEK293 cells indicated that HBV infection or TMG treatment significantly enhanced total O-GlcNAcylation and YTHDF2 O-GlcNAcylation, whereas the OGT inhibitor OSMI-1 downregulated both processes." (PMID 36765030, 2023). "However, YTHDF2 was also able to inhibit cell proliferation and tumor growth and activate ERK and MEK signaling by inducing the degradation of EGFR mRNA in hepatoma cells." (PMID 36360287, 2022).
hepatocellular carcinoma (continued). "Notably, we demonstrated a positive correlation between YTHDF2 expression and the infiltration of CD8+ T cells and macrophages in many tumors, and it was verified in 51 clinic hepatocellular carcinoma tissues." (PMID 36120577, 2022). "However, a previous study demonstrated YTHDF2 levels are restored in hypoxic states after siRNA knockdown of HIF1α in both the HEP3B and SMMC7721 hepatocellular carcinoma cell lines." (PMID 33616673, 2021). "In addition, YTHDF2 inhibits ERK/MAPK signaling by destabilizing EGFR mRNA and affecting hepatocellular carcinoma progression." (PMID 34660577, 2021). "This is consistent with previous findings on m6A-binding protein YTHDF2 and modulating the location and stability of EGFR mRNA at its 3’UTR site, enhancing the degradation of the EGFR mRNA, and playing an anti-tumor role in hepatocellular carcinoma." (PMID 34084770, 2021). "In addition, reducing YTHDF2 reduced m6A-containing IL11 and SERPINE2 mRNA in hepatocellular carcinoma to aggravate inflammation and vascular abnormalities." (PMID 33505426, 2020). "However, other studies show that YTHDF2 suppresses cell proliferation and growth via destabilizing the EGFR mRNA in hepatocellular carcinoma." (PMID 33505426, 2020). "In addition, it has been reported that YTHDF2 significantly disrupts the mRNA stability of ERGF and inhibits the proliferation and growth of hepatocellular carcinoma cells." (PMID 33505426, 2020). "In hepatocellular carcinoma (HCC), METTL3 suppresses SOCS2 expression in a YTHDF2-dependent manner, while WTAP reduces ETS1 mRNA levels through the m6A mechanism, collectively promoting cell cycle progression and tumor proliferation." (PMID 41446042, 2025). "Heat shock protein 90 beta (HSP90β) promotes the progression of hepatocellular carcinoma (HCC) by suppressing STIP1 homology and U‐box‐containing protein 1 (STUB1)‐induced YTHDF2 ubiquitination, which may inaugurate a novel intervention strategy for the treatment of HCC." (PMID 37515378, 2023). "Another study in hepatocellular carcinoma (HCC) cells found that METTL3 promoted proliferation by inhibiting the expression of SOCS2, a transcription factor that can negatively regulate cell proliferation, through m6A-dependent/YTHDF2-mediated mRNA degradation." (PMID 35350378, 2022). "In hepatocellular carcinoma (HCC), METTL3 enhances the degradation of m6A-containing SOCS2 mRNA together with YTHDF2." (PMID 32303268, 2020). "According to a recent study, the overexpression of YTHDF2 suppresses the activation of MEK and ERK in hepatocellular carcinoma cells (HCC)." (PMID 30875984, 2019). "YTHDF2 has also been shown to induce METTL3‐mediated suppressor of cytokine signaling 2 (SOCS2) mRNA degradation in hepatocellular carcinoma (HCC), therefore driving HCC cell proliferation, migration, and colony formation." (PMID 38721006, 2024). "Moreover, a study found that in hepatocellular carcinoma (HCC) cells, miR-145 regulated the level of m6A by targeting the 3′-UTR of YTHDF2 mRNA50." (PMID 34108450, 2021). "In hepatocellular carcinoma (HCC), METTL3-mediated increase in the m6A level of SOCS2 mRNA promotes degradation of this ubiquitous cytokine signaling transducer through an m6A YTHDF2-dependent mechanism; the decreased expression of SOCS2 promotes HCC progression." (PMID 34105069, 2021). "YTHDF2 knockdown significantly impaired cell growth, colony formation, and motility in HBV-infected hepatoma lines, functions that were restored by wild-type but not the S263A YTHDF2 mutant." (PMID 41227388, 2025). "In hepatocellular carcinoma (HCC), YTHDF2 has a dual role: it increases the stemness and tumor growth of liver cancer stem cells (LCSCs) by increasing the translation of OCT4, but it also inhibits the proliferation and growth of HCC cells by decreasing the stability of EGFR." (PMID 38351531, 2024).
liver cancer (70 papers, 2019 to 2025). An epithelial or non-epithelial malignant neoplasm that arises from the liver. "In our research, PA2G4 was found to promote EMT of liver cancer cells by stabilizing mRNA of FYN in a YTHDF2 dependent manner, and was an independent risk factor for recurrence." (PMID 35526051, 2022). "Importantly, our study proposes that targeting OGT-mediated YTHDF2 O-GlcNAcylation may be a novel strategy for the potential treatment of HBV-associated liver cancer." (PMID 36765030, 2023). "Further research is needed to clarify how YTHDF2 orchestrates the translation of specific immune-related mRNAs and its broader role in liver cancer immunotherapy." (PMID 39911396, 2025). "METTL3 facilitates m6A modification of suppressor of cytokine signaling 2 (SOCS2) and promotes its mRNA degradation through a YTHDF2-dependent pathway, thereby regulating the progression of liver cancer." (PMID 40495163, 2025). "Despite these promising findings, the precise mechanisms by which YTHDF2 regulates translation and modulates immune responses in liver cancer remain to be fully elucidated." (PMID 39911396, 2025). "By modulating the translation of these immune-related genes, YTHDF2 plays a pivotal role in controlling immune responses within the liver cancer microenvironment, allowing for more effective immune surveillance." (PMID 39911396, 2025). "In liver cancer, YTHDF2 increases the m6A level in the 5′UTR of OCT4 mRNA leading to enhanced protein translation of OCT4, and mutation in the corresponding m6A modification site decreases OCT4 expression." (PMID 38560499, 2024). "Numerous studies have confirmed the involvement of YTHDF2 in the development and progression of various diseases, including glioblastoma, liver cancer, and malignant glioblastoma, highlighting that YTHDF2 plays a crucial role in various diseases." (PMID 38711079, 2024). "Administration of a HIF-2α antagonist (PT2385) can restore the epigenetic mechanism of YTHDF2 programming and inhibit liver cancer." (PMID 38166832, 2024). "On one hand, YTHDF2 has been shown to support the phenotype of liver cancer stem cells and facilitate metastasis by enhancing the stability of m6A modifications on OCT4 transcripts." (PMID 38239038, 2024). "YTHDF2 mediated-m6A modification on pluripotent maker OCT-4 strengthens CSC phenotype of liver cancer and induces tumor metastasis." (PMID 37283789, 2023). "Another study also showed that YTHDF2 promotes the liver cancer stem cell phenotype and cancer metastasis in liver cancer by regulating OCT4 mRNA in an m6A-dependent manner." (PMID 39872957, 2023). "It has been reported that OCT4 is a downstream effector for YTHDF2 regulating liver cancer stem cell phenotype via m6A RNA methylation." (PMID 37515378, 2023). "Transcriptionally, the hypoxia-induced HIF1α/2α signaling pathway can negatively regulate YTHDF2 expression to favor tumor growth in liver cancer." (PMID 37012388, 2023). "Specially, YTHDF2 was found to promote the liver cancer stem cell phenotype and lung metastasis by enhancing the translation of OCT4 mRNA, and was an independent risk factor for recurrence after hepatectomy." (PMID 35526051, 2022). "Research shows that METTL3 promotes cancer progression through YTHDF2 dependent posttranscriptional silencing of SOCS2 in liver cancer." (PMID 35595748, 2022). "Such as, METTL3 promotes liver cancer progression by regulating SOCS2 in an YTHDF2-dependent manner." (PMID 36008805, 2022). "Silencing of YTHDF2 accelerated tumor inflammation and vascular abnormalities, thereby promoting the tumor growth, metastasis, and vascular remodeling of liver cancer." (PMID 35382893, 2022). "In purified CD133+ liver cancer stem cells, knockdown of YTHDF2 impaired tumor-initiating ability; in contrast, overexpression of YTHDF2 exerted the opposite effect." (PMID 35859892, 2022).
liver cancer (continued). "For instance, in liver cancer, YTHDF2 promoted the phenotype of cancer stem cell and cancer metastasis through regulation in m6A methylation of pluripotency factor OCT4 mRNA." (PMID 36545327, 2022). "Highly expressed YTHDF2 can promote the proliferation and migration of liver cancer cells, increase the number of liver cancer stem cells (CSCs), and enhance the tumor burden and lung metastasis in vivo." (PMID 35382893, 2022). "The ectopic expression of OCT4 was capable to restore the impaired stemness caused by YTHDF2 depletion, suggesting that YTHDF2 induced m6A-OCT4 to promote liver cancer stemness." (PMID 36009465, 2022). "For instance, YTHDF2, an m6A reader protein, promotes the proliferation of liver cancer tumor stem cells and promotes tumor metastasis." (PMID 36411870, 2022). "It was also proven that YTHDF2 causes m6A-mediated SOCS2 mRNA degradation and contributes to liver cancer progression." (PMID 33726814, 2021). "There have been reports suggesting that YTHDF2 plays oncogenic role in cancer stem cells but suppresses the proliferation of differentiated tumor cells in liver cancer." (PMID 34246306, 2021). "YTHDF2 promotes the liver cancer stem cell phenotype and cancer metastasis by promoting OCT4 expression." (PMID 33390849, 2021). "Previously, another group has shown that the m6A modification was involved in promoting liver cancer progression through YTHDF2‐mediated SOCS2 degradation." (PMID 32368828, 2020). "Administration of a HIF-2α antagonist (PT2385) restored YTHDF2-programed epigenetic machinery and repressed liver cancer." (PMID 31735169, 2019). "For example, YTHDF2 can accelerate the degradation of mRNA transcripts for immune-suppressive molecules, such as PD-L1, which reduces immune suppression and enhances the immune system’s ability to target and eliminate liver cancer cells." (PMID 39911396, 2025). "In addition to regulating mRNA degradation, YTHDF2 influences the expression of surface antigens on liver cancer cells, thereby increasing the tumor’s visibility to the immune system." (PMID 39911396, 2025). "Notably, YTHDF2 levels positively correlated with α‐fetal protein levels, tumor size and advanced Barcelona Clinic Liver Cancer stages." (PMID 38247171, 2024). "In conclusion, YTHDF2 may be an important biomarker for the diagnosis and prognosis of liver cancer." (PMID 38166832, 2024). "YTHDF2 can also promote immune evasion and angiogenesis in liver cancer by recognizing the m6A modification site in the 5’UTR of ETS variant transcription factor 5 mRNA and recruiting the eukaryotic translation initiation factor 3 subunit B to facilitate its translation." (PMID 39593172, 2024). "Our results also revealed that YTHDF2 might play an important role in liver cancer development and could be used as a therapeutic target for HCC patients." (PMID 36936652, 2023). "Importantly, the use of HIF-2α antagonist restored YTHDF2-programed epigenetic machinery and repressed liver cancer." (PMID 37369946, 2023). "In gastric cancer (GC), liver cancer and lung cancer, YTHDF2 was found to be both upregulated and downregulated, suggesting that YTHDF2 may play a dual role as both an oncogene and tumor suppressor." (PMID 37612540, 2023). "Furthermore, we found that YTHDF2 was O-GlcNAcylated at Ser263 and emphasized its oncogenic activity in liver cancer." (PMID 36765030, 2023). "Moreover, the methyltransferase METTL3 was discovered to regulate the degradation of SOCS2 mRNA, enhancing the progression of liver cancer in a YTHDF2-mediated m6A-dependent manner." (PMID 34996459, 2022). "In addition, different readers can play opposite roles in the same cancer; IGF2BP1 is an important protumorigenic factor in pancreatic cancer, nevertheless, YTHDF2 is poor expressed in liver cancer and inhibits cancer cells proliferation and growth." (PMID 35915142, 2022).
liver cancer (continued). "It was demonstrated that high expression of YTHDF2 in liver cancer cells could significantly reduce the phosphorylation levels of ERK and mitogen-activated protein kinase kinase (MAPKK/MEK)." (PMID 35382893, 2022). "The knockdown of YTHDF2 could significantly inhibit the tumor-initiating ability of CD133+ liver cancer stem cells, while the overexpression of YTHDF2 exerted the opposite effect." (PMID 36009465, 2022). "YTHDF2 was also found to be both upregulated and downregulated in lung cancer, GC, and liver cancer, which indicated that YTHDF2 might play a dual role as both an oncogene and tumor suppressor." (PMID 35382893, 2022). "Future studies should demonstrate the specific effect of YTHDF2 on liver cancer and the involved signaling pathway, and also determine whether YTHDF2 is a tumor suppressor or a cancer-promoting factor." (PMID 33692959, 2021). "Knockdown of YTHDF2 resulted in impaired stemness in liver cancer cells." (PMID 34539889, 2021). "The Cox risk score and clinical characteristic analysis confirmed that ZC3H13, METTL13, and YTHDF2 could be used as prognostic indicators and even as targets for new treatment of liver cancer." (PMID 34055974, 2021). "YTHDF2′s role in liver cancer is still controversial, with some data showing its downregulation and consequential decreased cell proliferation during hypoxia in HCC cells lines, while others reported an upregulation of YTHDF2 in HCC correlating with a poor survival." (PMID 34502337, 2021). "Indeed, another research group regarded YTHDF2 as an oncogene in HCC because they found that YTHDF2 increased OCT4 expression to promote liver cancer metastasis." (PMID 33795663, 2021). "In addition, YTHDF2 is closely related to the degree of malignancy of liver cancer, and regulates mRNA degradation by recognizing m6A sites, resulting in the enhancement of liver cancer cell proliferation." (PMID 33540684, 2021). "In contrast, some studies have shown that YTHDF2 could inhibit the progression of liver cancer by stabilizing EGFR or IL-11 mRNA." (PMID 33519919, 2020). "As reported in previous research, METTL3 promotes liver cancer progression through YTHDF2." (PMID 31824761, 2019). "Ultimately, targeting YTHDF2 could serve as a promising approach to improve treatment outcomes and survival rates for patients with liver cancer, offering a more effective means of overcoming immune suppression and enhancing immune cell-mediated tumor clearance." (PMID 39911396, 2025). "However, the specific role of YTHDF2 in liver cancer needs further study." (PMID 38166832, 2024). "Furthermore, the role of YTHDF2 in liver cancer is controversial." (PMID 34692544, 2021). "In liver cancer, METTL3 promotes the expression of SOCS2 through YTHDF2 dependent enhancement of SOCS2 m6A modification, which in turn induces lung metastasis of liver cancer." (PMID 40097750, 2025). "YTHDF2 also promotes the cancer stem cell (CSC) phenotype and metastasis via regulating m6A methylation of OCT4 mRNA and protein expression in liver cancer cells." (PMID 39135292, 2024). "In liver cancer, METTL3 participates in RNA decay by facilitating the binding of m6A reader YTHDF2 to the SOCS2 gene, ultimately promoting cancer cell proliferation and migration." (PMID 38966069, 2024). "We also constructed a score model including YTHDF1 and YTHDF2 in LIHC, and divided the liver cancer patients into a high-score group and a low-score group." (PMID 37833468, 2023). "In hepatoblastoma, a rare liver cancer usually diagnosed during the first 3 years of life, the upregulation of METTL3, YTHDF2, and FTO has been correlated with poor clinical outcomes." (PMID 37369946, 2023). "Mechanistically, YTHDF2 bound to m6A-modified OCT4 mRNA and increased its translation in liver cancer." (PMID 36009465, 2022). "METTL3 was reported to promote liver cancer progression; mechanistically, METTL3 increased SOCS2 mRNA m6A abundance, leading to SOCS2 mRNA degradation, which was mediated by YTHDF2." (PMID 36009465, 2022).